POU5F1B (POU class 5 homeobox 1B)
Description:
Shows weak transcriptional activator activity.
Synonyms: OCT4PG1; OTF3C; OTF3P1; POU5F1P1; POU5FLC20; POU5FLC8; OCT4-PG1; POU5F1P4
Tractability: No criterion of Open Targets' tractability assessment is met for any kind of drug.
Gene: Protein-coding gene on chromosome 8 (127,322,183 to 127,420,066, forward strand). Ensembl gene ENSG00000212993.
Subcellular location: Nucleus; Cytoplasm
Subcellular location (Human Protein Atlas): Nucleoplasm; Cytosol; Mitochondria
Gene Ontology:
Molecular function: DNA-binding transcription factor activity; DNA-binding transcription factor activity, RNA polymerase II-specific; RNA polymerase II cis-regulatory region sequence-specific DNA binding; DNA binding
Biological process: regulation of DNA-templated transcription; regulation of transcription by RNA polymerase II
Cellular component: cytoplasm; cytosol; nucleoplasm; chromatin; RNA polymerase II transcription regulator complex; nucleus
Genetic constraint (gnomAD): Loss-of-function variants: 25 observed, 27 expected, observed/expected ratio (o/e) 0.93, 90% interval 0.67 to 1.29. The synonymous counts are far from expectation, so gnomAD's model fits this gene poorly and the ratio says little. Missense variants: 451 observed, 415.85 expected, observed/expected ratio (o/e) 1.08, 90% interval 1 to 1.17. Synonymous variants: 220 observed, 172.41 expected, observed/expected ratio (o/e) 1.28, 90% interval 1.14 to 1.43.
Homologues: Orthologues: chimpanzee POU5F1B (96% identical), rabbit POU5F1 (87% identical), guinea pig Pou5f1 (82% identical), rat Pou5f1 (81% identical), mouse Pou5f1 (81% identical), dog POU5F1 (71% identical), zebrafish pou5f3 (42% identical), Drosophila melanogaster vvl (36% identical), zebrafish pou3f1 (33% identical), tropical clawed frog pou3f1 (32% identical), Caenorhabditis elegans ceh-18 (28% identical), Drosophila melanogaster acj6 (25% identical), and 1 more. Paralogues in human: POU5F1 (96% identical), POU5F2 (39% identical), POU3F3 (36% identical), POU2F1 (35% identical), POU3F4 (34% identical), POU3F1 (34% identical), POU3F2 (33% identical), POU2F2 (31% identical), POU2F3 (30% identical), POU1F1 (26% identical), POU4F3 (26% identical), POU4F1 (25% identical), and 5 more.
Diseases named in the same sentence as POU5F1B in open-access papers:
POU5F1B is named in the same sentence as 33 diseases in open-access papers, as found by Europe PMC text mining. Sharing a sentence is not in itself a finding about the gene and the disease. The quoted sentences say what the papers report.
gastric cancer (14 papers, 2014 to 2023). A primary or metastatic malignant neoplasm involving the stomach. "POU5F1B is known to be associated with mRNA abundance and an aggressive phenotype in gastric cancer." (PMID 26360582, 2015). "POU5F1B was shown to be overexpressed in gastric cancer and its knockdown confirmed a role for POU5F1B in the promotion of tumor cell growth." (PMID 35176995, 2022). "Previous studies proved that POU5F1B promotes tumor growth and aggressiveness in several cancers, including gastric cancer and CRC." (PMID 34934770, 2021). "For example, in gastric cancer (GC), overexpressed POU5F1B was found to stimulate the occurrence and growth of tumors in vivo." (PMID 32436945, 2020). "For example increased levels of OCT4 pseudogene POU5F1B has been reported to promote tumor growth and predict poor prognosis in stage IV gastric cancer patients." (PMID 30219035, 2018). "Overexpression of POU5F1B in gastric cancer cells promotes colony formation in vitro and tumor growth in vivo." (PMID 30071685, 2018). "A recent study showed that the POU5F1B promotes an aggressive phenotype of gastric cancer." (PMID 37667739, 2023). "Furthermore, high expression of another OCT4 pseudogene POU5F1B (POU domain class 5 transcription factor 1B) enhances cancer cell proliferation and tumuorigenesis in gastric cancer." (PMID 27561207, 2017). "POU5F1B TcGTs generally correlating with a higher level of POU5F1B expression were most frequent in CRC samples, but also commonly detected in several other tumors, including prostate, uterus, breast, lung and stomach cancers (right)." (PMID 35987910, 2022).
prostate carcinoma (13 papers, 2014 to 2022). A carcinoma that arises from epithelial cells of the prostate gland. "Further, the methylation level near the POU5F1B gene and the genetic variation around that region were found to be associated with the prostate cancer risk." (PMID 35176995, 2022). "POU5F1B is expressed in normal prostate tissue and is overexpressed in prostatic carcinoma, compared to normal prostatic tissue surrounding the carcinoma." (PMID 29560112, 2018). "Many studies have reported aberrations in POU5F1B in cancer, such as in gastric and prostate cancer." (PMID 28719033, 2017). "POU5F1B has been suggested to be involved in prostate cancer pathogenesis." (PMID 35729236, 2022). "Common genes (e.g. MYC and POU5F1B) were identified in both prostate cancer cell lines." (PMID 26934861, 2016). "Several other genes and ncRNAs at 8q24, such as POU5F1B (previously thought to be a pseudogene), PRNCR1, CASC11 and CCAT2, have also been shown to be overexpressed in prostate cancer and may also play a role in the development or progression of prostate cancer." (PMID 33374332, 2020).
breast carcinoma (6 papers, 2014 to 2024). "The data show an upregulation of breast cancer related genes in T1 and C1 relative to 10A, including LRATD2, PCAT1, CASC19, CASC8, POU5F1B, PVT1 and MYC on chromosome 8." (PMID 38076897, 2024). "Besides, even protein-coding genes linked to breast cancer susceptibility, like NEK10 (P-value 1.6 × 10-5, overlapping with SLC4A7) or POU5F1B, were absent from the PPIN." (PMID 33735170, 2021).
colorectal cancer (5 papers, 2014 to 2025). A primary or metastatic malignant neoplasm that affects the colon or rectum. "For example, in colorectal cancer, the oncogene POU5F1B has been shown to be expressed through the control of an ERV LTR promoter, and to lead to the development of larger tumors in mice." (PMID 41065417, 2025). "To investigate the functional consequences of POU5F1B upregulation in colorectal cancer, we used a combination of in vitro and in vivo studies." (PMID 35987910, 2022). "Adding to the involvement of risk alleles on MYC, our analysis also highlighted rs6983267, which has been shown in colorectal cancer to interact with MYC and rs4242382, affecting the expression of MYC and POU5F1B." (PMID 29560112, 2018).
cervical carcinoma (3 papers, 2020 to 2025). A carcinoma arising from either the exocervical squamous epithelium or the endocervical glandular epithelium. "POU5F1B (POU class 5 homeobox 1B), a pseudogene associated with OCT4, has been identified as having oncogenic potential, particularly in cervical cancer." (PMID 40568269, 2025). "The authors confirmed that interference with expression of POU5F1B significantly suppressed cell proliferation, migration and invasion, and induced apoptosis in cervical cancer." (PMID 32185172, 2020).
pancreatic ductal adenocarcinoma (3 papers, 2020 to 2022). An infiltrating adenocarcinoma that arises from the epithelial cells of the pancreas. "POU5F1B can promote cancer oncogenesis by cooperating with MYC and is associated with poor prognosis in pancreatic ductal adenocarcinoma patients." (PMID 35003220, 2021). "In addition, a recent study in pancreatic ductal adenocarcinoma has shown that high expression of ALCAM, POU5F1B, and SMO in CTCs is associated with a worse prognosis and with an increase of stemness markers POU5F1B, CD44, and ALCAM 3 months after palliative chemotherapy." (PMID 32192534, 2020).
colon cancer (1 paper, 2025). "Notably, TMEM220-AS1, TMEM238L, SOX6, SMAD7, TCF7L2, and PYGL were significantly downregulated in colon cancer, whereas LINC02257, PCAT1, CASC8, and POU5F1B were significantly upregulated in colon cancer." (PMID 41144378, 2025).
germ cell tumor (1 paper, 2016). A benign or malignant, gonadal or extragonadal neoplasm that originates from germ cells. "We found a correlation between PIM1/2 expression and VENTX, SOX15, UTF1, NANOG, POU5F1P4, POU5F1P3, and POU5F1B expression in male germ cell tumors." (PMID 27901106, 2016).
prostate tumor (1 paper, 2018). "Given the evidence of rs1447295 functionally altering expression of MYC and POU5F1B, its influence on prostate tumor progression and metastasis can be asserted." (PMID 29560112, 2018).
thyroid cancer (1 paper, 2020). "More recent studies have identified associations between the rs6983267 (POU5F1B, POU class 5 homeobox 1B and/or CCAT2, colon cancer associated transcript 2; 8q24) and thyroid cancer in different populations." (PMID 33551988, 2020).
cancer (27 papers, 2009 to 2026). A tumor composed of atypical neoplastic, often pleomorphic cells that invade other tissues. "Further illustrating the range of systems that the POU family play roles in we have POU5F1B, associated with terms in cluster 15, which has been found to have roles in cancer cells both in vitro and tumours in vivo." (PMID 35078412, 2022). "rs6983267 resides in the intronic region of POU5F1B, which encodes a transcriptional activator implicated in multisite cancers." (PMID 33551988, 2020). "Genome-wide association studies (GWAS) have shown the gene POU5F1B and several genetic variants or SNPs (Regions R1, R2, R3) that are risk factors for various cancers including CLL exist in this region." (PMID 23369149, 2013). "However, the finding that in other cancers, POU5F1B-encoding TcGTs can arise from TE integrants situated downstream of LTR66 argues for a strong selective pressure for expression of this protein irrespective of the underlying mechanism." (PMID 35987910, 2022). "Here, the authors characterise cancer-specific transposable element-driven transpochimeric gene transcripts and highlight the role of POU5F1B in CRC growth and metastasis." (PMID 35987910, 2022). "Next, we examined the co-amplification and co-expression of EXOSC4 with HSF1, MYC, and POU5F1B, which are located on chromosomes 8q24.3, 8q24.21, and 8q24.21, respectively, in nine different cancer types." (PMID 35008922, 2022). "Meanwhile, we found that MYC and POU5F1B were co-amplified with EXOSC4 at a high frequency but co-expressed with low correlation in all nine cancer types." (PMID 35008922, 2022). "To probe for a broader role of POU5F1B in human cancer, we sought the presence of POU5F1B TcGTs in more than 9,500 samples from 32 tumor types represented in the TCGA RNA-seq dataset." (PMID 35987910, 2022). "Together, these data demonstrate that the tumor-preferential overexpression of POU5F1B through the onco-exaptation of normally silenced TE promoters is a widespread phenomenon in human cancer." (PMID 35987910, 2022). "It is well-studied that copy number amplification is a significant factor contributing to the upregulation of POU5F1B in several cancers." (PMID 34934770, 2021). "In The Cancer Genome Atlas (TCGA) cohort of CRC, we observed 6 per cent of POU5F1B copy number amplification in the cancer genomes." (PMID 34934770, 2021). "Also located in this region is the OCT4 pseudogene POU5F1B, which has been observed to amplify in cancers." (PMID 38756785, 2024). "Interestingly, two of these OCT4 pseudogenes, POU5F1P5 and POU5F1B, were found to be transcribed in cancer cells." (PMID 35176995, 2022). "Variants correlated at r2 > 0.9 with rs7812894 (n = 9) are eQTLs for POU5F1B, a gene overexpressed in cancer cell lines and cancer tissues, although its role in PCa development is unknown." (PMID 30397198, 2018). "Regarding copy number alterations, the amplification of locus 8q24.21, where oncogene MYC and stemness factor POU5F1B reside, was similarly present in the two claudin-low groups, but more prevalent in basal ER-negative/HER2-negative cancers." (PMID 37345027, 2023). "There is growing evidence that CTC population is extremely heterogeneous, with a small percentage of tumor cells, called cancer stem cells (CSCs) expressing CD44, ALCAM, POU5F1B, able to proliferate and form new tumors." (PMID 31552188, 2019). "The POU5F1B retrogene arose by retrotransposition of OCT4 in the last common ancestor of great apes, hence is absent in the mouse, the animal model most commonly used to study human cancers." (PMID 35987910, 2022).
tumor (18 papers, 2014 to 2026). "WNK2 upregulated POU5F1B mRNA and protein levels, while POU5F1B overexpression reversed the tumor-suppressive effects caused by WNK2 depletion." (PMID 41628111, 2026). "First, they suggest that the detection of POU5F1B RNA or protein in a CRC biopsy warrants aggressive management of the underlying tumor." (PMID 35987910, 2022). "We also detected the age-related effect of rs1867277 (FOXE1) conferring the higher risk for PTC in patients older than 55 years and the association of rs7267944 (DHX35) with PTC risk in males and that of rs6983267 (POU5F1B/CCAT2) with more advanced tumor pT stage." (PMID 33551988, 2020). "Specifically, in the tumor center, TFs such as POU5F1B (Oct4) and RUNX2 are likely maintaining stem cell-like properties and driving tumor cell proliferation." (PMID 41238550, 2025). "Third, blocking the trans-acting mediators released by POU5F1B-expressing cells could also be of benefit, as these molecules are predicted to increase the oncogenic properties of neighboring cells and of the tumor microenvironment." (PMID 35987910, 2022). "However, in TCGA cohort of CRC, 20 per cent of the tumor samples had higher expressed POU5F1B, while the amplification recurrence of POU5F1B gene bodies in CRC accounts for only 10 per cent." (PMID 34934770, 2021). "The transplanted tumor fragments themselves presented roughly similar masses and volumes at the implantation site, suggesting that the fitness of well-constituted tumors may be less critically dependent on POU5F1B than their initial establishment and growth." (PMID 35987910, 2022). "Second, probably, rs10505477 allele could alter the interactions between the CASC8 and its cognate gene POU5F1B (POU class 5 homeobox 1 pseudogene 1), an acknowledged tumor susceptibility gene, by regulating the binding of some transcription factors to promoter of POU5F1B gene." (PMID 27249003, 2016). "Genes located in this region, including MYC, POU5F1B and PVT1, were notorious for tumor progression." (PMID 35493106, 2022). "For example, POU5F1B, a pseudogene of the stem cell self‐renewal gene OCT4, is frequently amplified in cancer and has been shown to promote colony formation, tumorigenicity, tumor growth, angiogenesis, and cell proliferation." (PMID 36366788, 2023). "The tumor-restricted TcGT most frequently detected in our cohort initiated within a primate-specific LTR66 endogenous retroviral promoter on chromosome 8q24, spliced into several other TE inserts (AluSx1, LTR33, L2b, and MLT1F1) and ended in POU5F1B, a paralog of the POU5F1/OCT4 pluripotency gene." (PMID 35987910, 2022).
POU5F1B also shares sentences with these, for which no sentence is quoted: ovarian carcinoma (3 papers); adenoma (1); colon adenocarcinoma (1); dementia (1); head-neck cancer (1); hepatocellular carcinoma (1); ischemic heart disease (1); kidney cancer (1); laryngeal disease (1); leukemia (1); lung carcinoma (1); lymph node metastasis (1); melanoma (1); salivary carcinomas (1); seminoma (1); small cell lung carcinoma (1); stomach cancers (1); teratoma (1); testicular cancer (1); testicular tumor (1); type 2 diabetes (1).